HAS1 (hyaluronan synthase 1)
Diseases named in the same sentence as HAS1 in open-access papers (continued):
Sharing a sentence is not in itself a finding about the gene and the disease.
viral infection (2 papers, 2021 to 2024). "The upregulation of Has-1 suggests that OM-85 supports the de novo synthesis of long-chain HA, which has been described to reduce viral infections." (PMID 34829773, 2021).
adenoma (1 paper, 2021). A neoplasm arising from the epithelium. "In addition, HAS-1 was also detected in the tumor cells of a fraction of ACC (42%), but only occasionally and weakly in adenoma tumor cells (although this difference was not statistically significant)." (PMID 34066306, 2021).
adrenocortical tumors (1 paper, 2021). "Laminin α3 and HAS-1 were mostly expressed in smooth muscle and endothelial cells of the vascular network of both benign and malignant adrenocortical tumors." (PMID 34066306, 2021).
astrocytomas (1 paper, 2018). "Our results indicate that especially HAS2 and to a lesser extent HYAL2 and HAS1 are involved in the progression of diffusely infiltrating astrocytomas." (PMID 29914429, 2018).
breast tumors (1 paper, 2020). "Alterations in HAS1 (< 2%) and HAS3 (6%) were rare, suggesting that HAS2 is the most relevant HA synthase in breast tumors." (PMID 32774770, 2020).
chondrosarcoma (1 paper, 2015). A malignant cartilaginous matrix-producing mesenchymal neoplasm arising from the bone and soft tissue. "HAS1 immunostainings have shown notable levels of HAS1 in mesothelial cells, fibroblasts, and human chondrosarcoma cells." (PMID 25699059, 2015).
cognitive decline (1 paper, 2022). "This SNP has been previously identified in a block of eight correlated SNPs in CD33 significantly associated with cognitive decline in univariate analysis in the all-female cohort, with highly significant effects on hyaluronan synthase-1 (HAS1) expression in the temporal cortex." (PMID 35408990, 2022).
COVID-19 (1 paper, 2022). A disease caused by infection with severe acute respiratory syndrome coronavirus 2. "In addition, IL-13 upregulates the downstream hyaluronan synthase 1 (Has1) gene and promotes the deposition of hyaluronic acid (HA) polysaccharide in the lung parenchyma, which may be a new mechanism for the development of severe COVID-19." (PMID 36362440, 2022).
diabetes (1 paper, 2019). "Coding polymorphisms in the consensus Chr 17 area included those linked to cancer (Fndc1, Tiam2, Zdhhc14 Has1), growth and development (Igf2r, Afdn, Tiam2, T2), immunology or diabetes itself via the energetic electron transfer chain (Tiam2, Pde10A) or basal thermal metabolism." (PMID 31661517, 2019).
dry eye (1 paper, 2025). "To further investigate whether the meibum produced by Has1−/−; Has3−/− mice can successfully stabilize the tear film and protect the ocular surface against the deleterious effects of DED, we subjected adult wt and Has1−/−; Has3−/− mice to an experimental model of BAC-induced dry eye." (PMID 40736174, 2025).
endometrial tumors (1 paper, 2010). "The epithelial intensities of HAS1, HAS2 and HAS3 immunostainings were significantly stronger in endometrial tumors compared to normal endometrium (p = 0.001, p = 0.004 and p = 0.003, respectively)." (PMID 20875124, 2010).
endometrioid adenocarcinoma (1 paper, 2011). An adenocarcinoma characterized by the presence of malignant glandular epithelial cells resembling endometrial cells. "In endometrioid adenocarcinoma of uterine corpus, the HAS1, HAS2, and HAS3 were expressed in tumor cells as our previous report." (PMID 21904555, 2011).
endometrioid ovarian cancer (1 paper, 2022). "This applies to HAS1 and HAS2 to data of OS of patients with endometrioid ovarian cancer and of PFS of patients in grade 1." (PMID 35767191, 2022).
endothelial dysfunction (1 paper, 2023). In vascular diseases, endothelial dysfunction is a systemic pathological state of the endothelium (the inner lining of blood vessels) and can be broadly defined as an imbalance between vasodilating and vasoconstricting substances produced by (or acting on) the endothelium. "Moreover, miR-125a inhibits Hyaluronan Synthase 1, and clinical reports have shown that levels of hyaluronic acid reduced in patients with OSA, which is associated with inflammation and endothelial dysfunction in these patients." (PMID 37917636, 2023).
gastric cancer (1 paper, 2022). A primary or metastatic malignant neoplasm involving the stomach. "Consistently, either silencing HMMR or HAS1 significantly reduced the cell aggregation formation and increased the anoikis of gastric cancer cells, which suggested either HA or HMMR was necessary for cell–cell interaction of gastric cancer." (PMID 36002694, 2022). "Congruously, abdominal cavity injection of AGS cells with different HAS1 or HMMR expression also demonstrated HA was requisite for HMMR-mediated peritoneal implantation of gastric cancer." (PMID 36002694, 2022).
Hepatic steatosis (1 paper, 2026). Steatosis is a term used to denote lipid accumulation within hepatocytes. "Using loss-of-function studies, liver-specific inhibition of Has1 ameliorates hepatic steatosis, inflammation and fibrosis in vivo and in vitro." (PMID 41695466, 2026).
Hyperglycemia (1 paper, 2024). An increased concentration of glucose in the blood. "This might be due to the observation that HAS1-mediated synthesis of HA mainly occurs only under particular conditions, such as hyperglycemia." (PMID 38473817, 2024).
idiopathic pulmonary arterial hypertension (1 paper, 2019). A sporadic form of pulmonary arterial hypertension (PAH) characterized by elevated pulmonary arterial resistance leading to right heart failure. "HAS2 expression is increased in an animal model of pulmonary hypertension, but decreased in pulmonary arterial smooth muscle cells in idiopathic pulmonary arterial hypertension where HAS1 is responsible for enhanced hyaluronan." (PMID 29933044, 2019).
idiopathic pulmonary fibrosis (1 paper, 2024). Idiopathic pulmonary fibrosis (IPF) is a nonneoplastic pulmonary disease that is characterized by the formation of scar tissue within the lungs in the absence of any known cause. "Intriguingly, the expression of HAS1 in PI16−COL15A1− double-negative fibroblasts of healthy parietal pleural is shared by subpleural fibroblasts from the lungs of patients with idiopathic pulmonary fibrosis, but not those from healthy lung." (PMID 38212075, 2024).
infarction (1 paper, 2025). A localised pathological necrosis of tissue resulting from obstruction of the blood supply usually by a thrombus, an embolus, or vascular torsion. "Interestingly, while Has1 expression was elevated prior to infarction, this increase was no longer present 7 days post‐MI, whereas Has3 expression remained unchanged." (PMID 41250926, 2025).
inflammatory skin disorders (1 paper, 2024). "Other genes, such as IL-21R, GSDMC, CCR7, TLR9, HAS1/3, IL-17A, IL-22, and CXCL10, have been previously identified as genes associated with various inflammatory skin disorders." (PMID 38612783, 2024).
liver fibrosis (1 paper, 2023). "HAS3 knockout mice develop liver fibrosis similar to wild-type mice, suggesting that HAS1 or HAS2 is more likely to regulate liver fibrosis." (PMID 36930869, 2023).
lymphoma (1 paper, 2013). A malignant (clonal) proliferation of B- lymphocytes or T- lymphocytes which involves the lymph nodes, bone marrow and/or extranodal sites. "Furthermore, chemoresistant lymphoma cell lines were also found to have greater expression of Has1, Has2, and Has3 transcripts, and to secrete higher levels of HA." (PMID 24124770, 2013).
memory impairment (1 paper, 2025). "Treatment with 4‐MU reduced infarct volume and improved learning and memory impairments by downregulating HAS1 and HAS2." (PMID 41355840, 2025).
metabolic syndrome (1 paper, 2015). A cluster of metabolic risk factors for CARDIOVASCULAR DISEASES and TYPE 2 DIABETES MELLITUS. "Despite the apparently minor enzymatic activity of HAS1 under normal conditions, it may be an important factor under conditions associated with glycemic stress like metabolic syndrome, inflammation, and cancer." (PMID 25699059, 2015).
metastatic tumors (1 paper, 2025). "HAS1 and HAS3 expression is indeed increased in metastatic tumors of HFD-fed mice compared with LFD-fed mice." (PMID 39946200, 2025).
monoclonal gammopathy (1 paper, 2014). A condition characterized by the abnormal presence of monoclonal immunoglobulins in the blood or urine. "This is the first report that risk for B-cell malignancies and an inherited monoclonal gammopathy-prone phenotype is directly correlated with intronic HAS1 SNPs, likely by promoting aberrant HAS1 splicing." (PMID 24950197, 2014). "In the Icelandic family kindred, HAS1 SNPs were more frequent in affected members (those with monoclonal gammopathies or hype-responder phenotype) than in unaffected family members (p = .0005), confirming the association with risk in a four generation family having a shared genetic heritage." (PMID 24950197, 2014).
oral cancer (1 paper, 2017). "Although HAS3 appears to play a dominant role in oral cancer, we still can not rule out the involvement of HAS1 or HAS2 in HA synthesis nor explain why reduced HA staining was a poor prognositic maker in other oral cancer cohort." (PMID 28107185, 2017). "Despite the detection of both HAS1 and HAS2 in oral cancer cells, their expression levels were lower than that of HAS3 in most oral cancer cell lines not to mention that HAS1 and HAS2 are catalytically less active than HAS3 in HA synthesis." (PMID 28107185, 2017).
oral lichen planus (1 paper, 2015). Oral lichen planus is a chronic inflammatory oral condition of unknown aetiology characterized by T-cell-mediated chronic immune response and abnormal epithelial keratinization cycle. "It is worth noting that in oral lichen planus the increased HAS1 expression is detected in the basal layers of the epithelium, which is the most affected, inflamed area in lichen planus." (PMID 25699059, 2015). "Moreover, elevated HAS1 expression is observed in oral lichen planus, which is a chronic inflammatory disease of the oral mucosa." (PMID 25699059, 2015).
peritonitis (1 paper, 2023). Inflammation of the peritoneum (tissue that lines the abdominal wall and covers most of the organs in the abdomen). "Expression of the genes coding for HA synthases (Has1-3) and hyaluronidases (Hyal1, 3) was not significantly affected by peritonitis." (PMID 38094743, 2023).
radiation dermatitis (1 paper, 2025). "Therefore, in the future, we aim to further investigate the specific mechanism of action of HAS1 on radiation dermatitis and its role in other related diseases." (PMID 40394699, 2025).
Sepsis (1 paper, 2022). Sepsis is defined as life-threatening organ dysfunction caused by a dysregulated host response to infection. "In fact, early upregulation of HAS1 was observed consistently across all vascular surfaces, directly implicating HAS1 in glycocalyx remodeling during sepsis." (PMID 35913192, 2022).
squamous cell carcinoma (1 paper, 2015). A carcinoma arising from squamous epithelial cells. "Matched lung parenchyma tissuesamples included 25 squamous cell carcinomas and 31 adenocarcinomas.Immunohistochemistry was performed to analyze for the distribution of hyaluronidase(Hyal)-1 and −3, and hyaluronan synthases (HAS)-1, −2, and −3." (PMID 26352698, 2015). "For squamous cell carcinoma and adenocarcinoma, theproportion of HAS-1-positive cells was typically less than 20 (P=0.0001)." (PMID 26352698, 2015).
synovitis (1 paper, 2021). Inflammation of a synovial membrane. "At 12 h post-induction of synovitis, both HA synthase 1 (HAS1) (p = 0.024) and HA synthase 3 (HAS3) (p = 0.01) expression were decreased in the cell pellets of the synovitis MCJ as compared to the lavage TCJ." (PMID 33980227, 2021).
teratocarcinoma (1 paper, 2022). A germ cell tumor characterized by the presence of an embryonal carcinoma component and a teratoma component. "HAS1, HAS2 and HYAL3 expression levels showed to be comparable in all adenocarcinoma cell lines SKOV-3, Caov-3 and SW 626 cells, whereas the teratocarcinoma cell line PA-1 cells expressed higher levels of all the three genes." (PMID 35767191, 2022).
tuberculosis (1 paper, 2009). A chronic, recurrent infection caused by the bacterium Mycobacterium tuberculosis. "Taken together, these data indicate that the major hyaluronan synthase in the lungs is HAS1 both before and after M. tuberculosis infection and hyaluronan accumulates in the tuberculosis lesion." (PMID 19876387, 2009).
ulcerative colitis (1 paper, 2024). An inflammatory bowel disease involving the mucosal surface of the large intestine and rectum. "In particular, nicotinamide phosphoribosyltransferase (R = 0.515, p = 0.020) and hyaluronan synthase 1 (R = 0.531, p = 0.016) exerted significant correlations with the presence of ulcerative colitis." (PMID 38256678, 2024).
tumor (42 papers, 2005 to 2026). "HAS1 encodes hyaluronic acid, and its upregulation potentiates tumor development and progression by remodeling the TME59." (PMID 38600248, 2024). "Similar works showed that HAS1 modulates HA and CD44 levels, affecting tumor growth and progression in BC, and HAS1 mRNA expression was associated with BC metastasis." (PMID 38372785, 2024). "HAS1 is an enzyme involved in expression of hyaluronan, an important component of the extracellular matrix, and a hyaluronan-rich tumor microenvironment is associated with enhanced malignancy and poor prognosis in cancer patients." (PMID 37005447, 2023). "Expression of several other genes upregulated by ruxolitinib such as Csf2, Cx3cl1, Cx3cr1, Has1, and Ccl22 in myeloid cell populations is known to be associated with tumor progression, myeloid cell accumulation, and tumor progression." (PMID 37005447, 2023). "More intriguingly, HAS-1 expression in ACC tumor cells was associated with a lower mitotic rate, a lower prevalence of atypical mitotic figures and a better outcome." (PMID 34066306, 2021). "Our data, in line with previous reports, showed increased HAS1 expression to be associated with invasive tumor growth and high malignity in BC.In this regard HAS1 was significantly upregulated in muscle-invasive tumors and in dedifferentiated G3 high grade compared to G1-2 low grade BC." (PMID 24069434, 2013). "HAS1 expression was significantly higher in the tumor stage compared to the patch stage, whereas expression of HAS2 and HAS3 was moderate to strong in all disease stages." (PMID 39858106, 2025). "Immunohistochemical staining of serial OSCC sections revealed that IF with high HAS1 expression showed markedly lower E-cadherin and higher N-cadherin levels in tumor epithelial cells, compared to HAS1-low regions." (PMID 40813707, 2025). "To assess the potential role of HAS1 expression in CAFIF-dependent OSCC tumor progression, we used lentiviral transduction to achieve a stable knockdown of HAS1 mRNA expression in CAFIF." (PMID 40813707, 2025). "Similar to normal mammary glands, CD45-/CD90.2 + fibroblasts specifically expressed Has1 whereas EpCAM + epithelial cells expressed elevated levels of Has3 in the HC11/R1-LM tumor model." (PMID 36723776, 2023). "In recent years, numerous studies have investigated the relationship between HAS1 and tumorigenesis, revealing that HAS1 plays a crucial role in malignant transformation and tumor growth." (PMID 37509716, 2023). "For instance, inhibition of HAS1 induced apoptosis in bladder cancer in vitro, thus inhibiting tumor growth and angiogenesis." (PMID 36936902, 2023). "The fact that low expression of HAS2 is correlated with lower tumour cell growth is strengthened by the results of String analysis that HAS1-3 interact close with UGDH." (PMID 35767191, 2022). "In this study, we examined the mRNA expression of the HAS family members (HAS1, 2, and 3) in paired tumor (T) vs. normal (N) tissue samples by real-time PCR analysis." (PMID 34770956, 2021). "We also show that HAS1, HAS2 and HYAL2 are associated with WHO grade, suggesting that they have a role in tumor progression." (PMID 29914429, 2018). "Immunostainings of Has1 in developing tissues and HAS1 in tumor tissues, endometrium, and oral mucosa have been published recently." (PMID 25699059, 2015). "Previous studies revealed that increased HAS1 isoenzyme and Hyal1 expression in human BC were predictive for muscle-invasive tumor growth, metastasis and poor disease-specific survival." (PMID 24069434, 2013). "Importantly, our data indicate that bexarotene reduces LMWHA and HMWHA accumulation by suppressing the expression of HAS1, HAS3, and CEMIP in tumor cells and HAS1 and HAS2 in fibroblasts." (PMID 39858106, 2025). "We then explored the function of HAS1 expression on tumor cell regulation." (PMID 40813707, 2025).